ZEB1 (zinc finger E-box binding homeobox 1)
Diseases named in the same sentence as ZEB1 in open-access papers (continued):
Sharing a sentence is not in itself a finding about the gene and the disease.
breast carcinoma (continued). "Our data uncover the ZEB1/ERα-miR-190-SOX9 axis and suggest a mechanism by which the Wnt/β-catenin signaling pathway is involved in breast cancer anti-estrogen therapy." (PMID 30658681, 2019). "Datasets included comparison of ZEB1 overexpression in the 393P murine cells, miR-200 overexpression in murine 344SQ cells, ZEB1 knockdown in human MDA-MB-231 breast cancer cells, and ZEB1 overexpression in 3T3-L1 pre-adipocytes." (PMID 31719531, 2019). "By contrast, OSCC cells with low levels of ZEB1/2, and high levels of E-cadherin and ESRP1/2 exhibited epithelial-like traits with FGFR(IIIb) isoforms, similar to the luminal-like subtype of breast cancer." (PMID 31682640, 2019). "We then substantiated ZEB1-regulated expression of ATM at mRNA and protein levels and in human breast cancer." (PMID 29352223, 2018). "In breast cancer, LncRNA ATB regulates ZEB1 and ZNF-217, inducing epithelial mesenchymal transition, which leads to trastuzumab resistance and increased invasion and metastasis." (PMID 29599647, 2018). "Higher levels of ESRP1, as well as higher ratios of ESRP1/ZEB1 and/or ESRP1/HAS2, canpredict poor survival in multiple breast cancer datasets." (PMID 31069317, 2018). "ZEB1 also regulates tumor metastasis through the ZEB1/EMT axis in hepatoma, breast cancer, and colorectal cancer." (PMID 29426364, 2018). "Our data uncover the ZEB1-miR-190-SMAD2 axis and provide a mechanism to explain the TGF-β network in breast cancer metastasis." (PMID 29510731, 2018). "The miR-200 family regulates EMT by targeting the ZEB1/2-E-cadherin axis, whereas in other studies, elevated levels of miR-200 family have induced EMT and promoted metastasis in breast cancer." (PMID 29996899, 2018). "Previous reports indicated that the upregulation of ZEB1 by TGF-β or other cytokines/growth factors is accompanied by ZEB2 upregulation, and that both ZEB1 and ZEB2 are highly expressed in breast cancer cells with aggressive phenotypes." (PMID 29969465, 2018). "In breast cancer cells repression of ZEB2, independently of ZEB1, resulted in reduced expression of a mesenchymal marker, Vimentin and reduced invasion." (PMID 29963231, 2018). "We confirmed this knowledge by querying the expression of ZEB1 (and its related transcription factor ZEB2) in several human breast cancer cell lines based on data available in the GOBO database." (PMID 29744893, 2018). "To determine the correlation between ZEB1 and ATM expression in human breast cancer, we performed immunohistochemical staining in 139 cases of primary breast carcinoma." (PMID 29352223, 2018). "The uncovering of this ZEB1-miR-190-SMAD axis will extend our comprehension of TGF-β network complexity and miR-190 as a new option to target TGF-β signaling for breast cancer intervention." (PMID 29510731, 2018). "Expression of ZEB1 and HAS2, the main synthase of HA in tumor cells, was strongly correlated in breast cancer cell lines and tumor patient samples and high expression levels of HAS2 were associated with poor survival." (PMID 28086235, 2017). "Our findings indicated that ZEB1 and partly ZEB2 regulated the characteristic inflammatory phenotype of breast cancer cells, in part through IL‐6 and IL‐8." (PMID 28618162, 2017). "The importance of this finding is that the loss of ER-α in breast cancer patients is indicative of a poor prognosis, and this reduced expression or absence of ER-α caused by ZEB1 may have implications for ER-α-negative and/or antiestrogen-resistant breast cancers." (PMID 28383555, 2017). "Several transcription factors, such as Snail, Twist and ZEB1, had been reported to promote EMT in multiple tumors, including breast cancer." (PMID 28583190, 2017). "Thus, ZEB1-mediated down-regulation of Lgl2 may play a role in breast cancer metastasis." (PMID 28356139, 2017).
breast carcinoma (continued). "Here, we identified a ZEB1‐regulated inflammatory phenotype in breast cancer cells using chromatin immunoprecipitation sequencing and RNA sequencing, followed by gene set enrichment analysis (GSEA) of ZEB1‐bound genes." (PMID 28618162, 2017). "We have shown in breast cancer cells that suppression of proliferation by EMT is mediated at least in part through ZEB1 repression of MYB, a gene important in driving proliferation of estrogen receptor (ER)-positive primary breast cancers." (PMID 28750639, 2017). "In this study, we provide evidence that ZEB1 promotes CSC self-renewal in vitro and in vivo, thus leading to increased breast cancer initiation and growth." (PMID 28903350, 2017). "In conclusion, together with our previous findings, the analysis provides insights into a complex multi-factorial feedback system controlled by ZEB1 to induce EMT and metastatic behavior of breast cancer cells." (PMID 28086235, 2017). "It was further observed that the up-regulation of ZEB1 and ZNF217 by lnc-ATB further augmented the EMT effects in breast cancer cells." (PMID 29299178, 2017). "Downregulation of E-cadherin is one of the critical markers of EMT in human breast cancers, and FOXC2, Twist, ZEB1, ZEB2, Slug, and Snail are transcription factors that repress E-cadherin transcription." (PMID 28212558, 2017). "First, we found that ZEB1 interacts with DNMT3B and HDAC1 at the ER-α promoter, leading to DNA hypermethylation and the downregulation of ER-α in breast cancer cells." (PMID 28383555, 2017). "We identified hyaluronic acid (HA), one major ECM proteoglycan and enriched in mammary tumors, to support EMT and enhance ZEB1 expression in cooperation with CD44s." (PMID 28086235, 2017). "Zinc finger E-box-binding homeobox, ZEB1, is a well-studied transcription factor involved in Epithelial-Mesenchymal Transition (EMT) in several cancer types, including breast cancer, lung cancer, pancreatic cancer and prostate cancer." (PMID 27411336, 2016). "To further substantiate a link between ZEB1, VEGFA and tumor angiogenesis, we performed immunohistochemical staining for ZEB1, VEGFA, and CD31 in 228 cases of human breast carcinoma." (PMID 26882471, 2016). "The mRNA expression of ZEB1, YAP and genes of the common ZEB1/YAP target set is significantly correlated in human breast cancers." (PMID 26876920, 2016). "Possibly, ZEB1 functions to inhibit PP2A (protein phosphatase 2A), which consequently promotes p38 phosphorylation in breast cancer cells." (PMID 26882471, 2016). "Analysis of the transcriptome of the 51 breast cancer cell lines showed an inverse relationship between expression of FUT1/3 and of SNAI2 and ZEB1/2." (PMID 26908442, 2016). "In breast cancer, another master EMT regulator, ZEB1, confers resistance to radiation therapy by allowing homologous recombination-dependent DNA repair through stabilization of CHK1." (PMID 27815674, 2016). "We further validated the translational and clinical relevance of a functional ZEB1/YAP interaction and its common target gene activation by analysing human breast cancer data sets." (PMID 26876920, 2016). "We found that AESN (200 μg/mL) markedly attenuated N-cadherin, ZEB1, and vimentin expressions in MCF-7 breast cancer cells." (PMID 27136519, 2016). "We focused on breast cancer and particularly on those genes of the YAP target gene set that were most differentially regulated between control and ZEB1 knockdown cells and thus contributed most to the enrichment result." (PMID 26876920, 2016). "CDH2 (encoding N-cadherin), VIM (encoding vimentin), TWIST1/2 (products which are EMT transcriptional factors) and SNAI1, as well as ZEB1, are well known key players involved in EMT-like processes of breast cancers." (PMID 27617643, 2016). "Although ZEB1/CDH1 are repressed by miR-200b, restoration of ZEB1 expression in breast cancer cells expressing miR-200b was unable to modify their metastatic potential, suggesting additional mechanisms underlying metastasis." (PMID 27081085, 2016).
breast carcinoma (continued). "Breast cancer cells treated with HNK, miR-34a mimic alone and in combination exhibited cytoplasmic localization of Zeb1." (PMID 26359358, 2015). "The strong correlation between ZEB1 and LPAR1 was most prominent in primary tumors of patients with basal breast cancers." (PMID 26098771, 2015). "Mechanistically, ectopic expression of ZEB1 is sufficient to downregulate E-cadherin and to induce EMT in breast cancer by binding to the conserved E-boxes in E-cadherin promoter." (PMID 26057751, 2015). "More importantly, nested feedback circuits of miR-200c/ZEB1 and miR-200c/ZNF217/TGF-β/ZEB1 contribute to EMT correlated with trastuzumab resistance and metastasis of breast cancers." (PMID 25871474, 2015). "Our findings are consistent with previous reports identifying ZEB1 as a downstream target of IGF1R, potentially assisting EMT processes in breast cancer cells." (PMID 25749031, 2015). "We analyzed a publicly available mRNA and miRNA microarray dataset from 101 breast cancer patients and observed significant inverse correlations of miR-200c with its target genes MYLK, TKS5 and ZEB1." (PMID 26334100, 2015). "Several studies evaluated expression of EMT transcription factors (SNAIL, SLUG, ZEB1, ZEB2, TWIST1, and TWIST2) in breast cancer tissue sections." (PMID 26194471, 2015). "LPAR1/miR-21, ZEB1/miR-21 and LPAR1/ZEB1 pairwise correlations were determined using data from in three publically available human breast cancer databases containing both mRNA and microRNA data (GSE5460; GSE16391; GSE12276)." (PMID 26098771, 2015). "Analysis of gene expression 56 breast cancer cell lines from the Cancer Cell Line Encyclopedia (CCLE) panel also showed high positive correlations between MYLK/TKS5 and ZEB1." (PMID 26334100, 2015). "We observed that 54.16% of the basal breast cancer cell lines expressed LPAR1 and 37.5% expressed ZEB1 above the overall means." (PMID 26098771, 2015). "Overexpression of transcription factors (TF), including TWIST1, SNAIL1, SLUG, ZEB1 and/or FOXC1,2, can induce EMT in mammary epithelial cells and/or breast cancer cells as well." (PMID 26194471, 2015). "Overall our results demonstrate functional relationships between ZEB1 and miR-21 driving LPA-dependent metastasis through LPA1 in basal breast cancers." (PMID 26098771, 2015). "The miRNA miR-200c-3p also displayed a very late activation at 36 h and it is involved in regulating epithelial to mesenchymal transition (EMT) by targeting the genes ZEB1 and SIP1 in breast cancer in response to transforming growth factor (TGF)." (PMID 26763900, 2015). "All these results proved lnc-ATB functions as a ceRNA by regulating ZEB1 and ZNF217 expression in breast cancer." (PMID 25871474, 2015). "This implies that many of the genes specifically increased in bone metastases of breast cancer, e.g. the BMP-inhibitor FST, are dependent on ZEB1 mediated activation." (PMID 25973542, 2015). "For example, Slug, Twist, Snail and ZEB1 are important in E-cadherin repression, and thus regulating EMT, especially in breast cancer." (PMID 25749385, 2015). "We chose the human basal breast cancer cell lines MDA-MB-231, MDA-BO2 and Hs578T to analyze the role of LPA and LPA1 on ZEB1 expression in vitro and in vivo." (PMID 26098771, 2015). "We demonstrated that elevated ZEB1 and BMP-inhibitor expression is correlated with breast cancer bone metastasis." (PMID 25973542, 2015). "Recent studies have shown that ZEB1 and ZEB2 are direct targets of the miR-200 family in human breast cancer cells (MDA-MB-231), canine kidney cells (MDCK), murine models, and a NCI-60 panel of cell lines." (PMID 25367080, 2014). "We identified two regulators (ZEB1 and HSF2) and one target gene (RAB21) for the miR-183/-96/-182 cluster in breast cancer cell lines." (PMID 25394902, 2014). "The transcriptional factors, ZEB1 and ZEB2 were previously demonstrated to be regulated by miR-200c, and they were found to be reciprocally expressed in breast cancer." (PMID 25329395, 2014).
breast carcinoma (continued). "For the predicted TF signaling pathways, certain signaling pathways have been detected in other types of cancer; for instance, ZEB1 regulates hsa-miR-34a in lung cancer and hsa-miR-21 targets E2F2 in breast cancer." (PMID 25289101, 2014). "In summary, the current study demonstrated that overexpression of S100A16 gene promoted EMT via Notch1/ZEB1, ZEB2/EMT pathway in breast cancer cells." (PMID 25287362, 2014). "We also found a direct ZEB1-mediated repression of EPCAM in human pancreatic and breast cancer cell lines, indicating a conserved regulatory circuit." (PMID 23667256, 2013). "Of the CDH1 repressor genes, ZEB1 has been found by others to be the more-dominant EMT driver, important in stabilizing and maintaining the mesenchymal phenotype in breast cancer systems." (PMID 24283570, 2013). "We found a similar ZEB1-dependent repression of EPCAM expression in human pancreatic and breast cancer cell lines, mediated through direct binding of ZEB1 to the EPCAM promoter." (PMID 23667256, 2013). "Here we have identified an inverse relation between ZEB1 and MYB throughout these cell states, and also in the breast cancer cell lines MDA-MB-231 and MDA-MB-468." (PMID 24283570, 2013). "The focus of this study was underpinned by the common reactivation of ZEB1, ZEB2 and TWIST1 in aggressive and undifferentiated human breast cancers, especially in the newly identified claudin-low intrinsic subtype." (PMID 22654675, 2012). "Zinc finger E-box binding homeobox 1 (ZEB1) and ZEB2 are shown to be crucial EMT activators in breast cancer by inhibiting E-cadherin expression." (PMID 22200848, 2012). "A recent study showed that the expression of miR-200b, which targets both ZEB1 and ZEB2, was downregulated in the cells that undergo TGF-beta-induced epithelial to mesenchymal transition (EMT), and was lost in invasive breast cancer cells." (PMID 21682903, 2011). "Furthermore, zinc finger E-box binding homeobox 1 (Zeb1) directly enhances the transcription of PFKP, thereby contributing to epirubicin (EPI) and etoposide (ETOP) resistance in breast cancer." (PMID 40264038, 2025). "Similarly, suppression of vimentin and ZEB1 occurred when lncRNA TUSC8 competed with miR-190b-5p, that consequently led to the inhibition of metastasis in breast cancer." (PMID 39912983, 2025). "In a study, VISTA expression in breast cancer shows a negative correlation with the epithelial marker E Cadherin and a positive correlation with mesenchymal genes (Vimentin, Slug and Zeb1)." (PMID 40344465, 2025). "However, when Zeb1 expression was stably knocked out using CRISPR/Cas9 in M13HS tumor hybrids and parental HS578T-Hyg breast cancer cells, only moderate phenotypic changes were observed." (PMID 40806166, 2025). "Similarly, TMEM97 silencing in breast cancer cell lines MCF-7 and MDA-MB-231 elevated E-cadherin protein levels but reduced N-cadherin and vimentin along with other classic EMT markers such as ZEB1, Twist, Snail, and Slug." (PMID 39995975, 2025). "Importantly, even if some ZEB1 target genes are shared between melanoma and breast cancer cell lines, such as CDH1 and other EMT genes, our study reveals cell type-specific effects of ZEB1, through the regulation of melanocytic lineage-specific genes." (PMID 38519642, 2024). "Although primary breast cancer tumors were examined in these clinical datasets for expression levels of TDO2, AhR, and ZEB1, these genes may be expressed at even higher levels in circulating tumor cells (anchorage-independent condition)." (PMID 39311710, 2024). "Consistently, for breast cancer patients, higher expression of NOTCH3 was positively correlated with metastasis-free survival (MFS) (p = 0.0011, HR = 0.519), whereas the expression level of ZEB1 was negatively correlated with MFS (p = 0.00413, HR = 2.43)." (PMID 38164285, 2024). "Depending on the expression of the EMT inducer ZEB1, basal breast cancer cells switch between non-CSC and CSC states." (PMID 39695175, 2024).
breast carcinoma (continued). "We have previously reported that Ets transcription factors activated by ERK pathways promote transcription of ZEB1 and ZEB2 in breast cancer cells, though it is unlikely that overexpression of ZEB1 would activate ERK pathway, due to drastic reduction of cell proliferation." (PMID 39362647, 2024). "In breast cancer cells, PRMT1 plays a crucial role in mediating the asymmetric dimethylation of histone H4 at arginine 3 within the ZEB1 promoter, facilitating the transcriptional expression of ZEB1, a key factor in the EMT process." (PMID 38326807, 2024). "We previously reported that ZEB1/2 are positively correlated with the expression of mesenchymal marker proteins and the aggressiveness of various types of cancer cells, including those from human HNSCC and human breast cancer." (PMID 39362647, 2024). "Consistent with data in the literature, prolonged treatment with AXL inhibitors led to the partial restoration of epithelial morphology in mesenchymal breast cancer cells (not shown), repression of ZEB1 and reactivation of E-cadherin expression." (PMID 38172210, 2024). "NOTCH3 may inhibit the progress of breast cancer through a multi-layer system, and it may at least partially inhibit the expression of ZEB1 and inhibit the proliferation, migration and EMT in breast cancer cells by inducing miR-223." (PMID 38164285, 2024). "LINC00894 (ENST0000044489) is a non-coding RNA derived from the X chromosome; it regulates the expression of transforming growth factor-beta 2 (TGF-β2) and zinc finger E-box-binding homeobox 1 (ZEB1), which may affect tamoxifen resistance in breast cancer." (PMID 39060766, 2024). "In this regard, it is important to mention that ZEB1 has been shown as a direct transcriptional (co-)inducer of inflammatory gene expression, like IL6, IL8 and others in several cell types, such as breast cancer cells and fibroblasts, corneal fibroblasts, hematopoietic and myeloid cells." (PMID 38937629, 2024). "According to this possibility, CTBP2 repression of fatty acid in breast cancer requires the interaction with the transcriptional repressor ZEB1, which was never detected as a CTBP2 partner in our co-immunoprecipitation analysis in GBM cells." (PMID 36414381, 2023). "In summary, PAX5-miR-142-DNMT1/ZEB1 constructed a negative feedback loop to regulate the progression of breast cancer, which provided emerging strategies for breast cancer therapy." (PMID 37403081, 2023). "ZEB1 has been shown to function as a transcriptional activator in complex with other transcription factors, such as YAP and AP1-factors c-Jun and FOSL1 in breast cancer." (PMID 38111531, 2023). "Furthermore, using METABRIC data, we found positive correlations between expression of ZFP36 and genes associated with the stem-like phenotype, as TWIST1, TWIST2, SNAI1, ZEB1, ZEB2, ALDH1A and YAP1 in all breast cancer subtypes." (PMID 38274271, 2023). "This study aimed to clarify the role of ZEB1 in M13HS tumor hybrids that were derived from spontaneous fusion events between the M13SV1-EGFP-Neo human breast epithelial cells and HS578T-Hyg human breast cancer cells." (PMID 38139138, 2023). "Besides, ZEB1 was also reported to repress the expression of ER-α transcriptionally by forming a ZEB1/DNMT3B/ HDAC1 complex on the ER-α promoter, which led to its hypermethylation in breast cancer." (PMID 37403081, 2023). "Finally, powerful prognostic correlations originate from the recent analyses of cooperation mechanisms between FOSL1, ZEB1, and YAP in breast cancer." (PMID 37176013, 2023). "Taken together, we revealed a feedback loop of PAX5 and miR-142, which could affect breast cancer progression by regulating DNMT1 and ZEB1." (PMID 37403081, 2023).